FAH (fumarylacetoacetate hydrolase)
Diseases named in the same sentence as FAH in open-access papers (continued):
Sharing a sentence is not in itself a finding about the gene and the disease.
cancer (9 papers, 2017 to 2024). A tumor composed of atypical neoplastic, often pleomorphic cells that invade other tissues. "In addition to very rare germline variants in genes related to liver function, such as HOXC4, PRSS56, and CYP1A1, the patient carried two variants strongly predicted to be deleterious affecting BRCA1 and FAH, both genes associated with cancer predisposition." (PMID 32432034, 2020). "Second, pan-cancer co-expression analysis for miRNA-target interaction in HCC using starBase showed that miR-539 level negatively correlated with TAT, HPD, GSTZ1 and FAH expression (r = -0.221, r = -0.193, r = -0.123, r = -0.166)." (PMID 32542016, 2020). "In this context, it has been reported that proapoptotic genes, including FOS, FAH, and PRODH, are upregulated in the cancer cells of nonangiogenic NSCLC." (PMID 35267627, 2022).
genetic disorder (9 papers, 2017 to 2024). "Hereditary Tyrosinemia Type 1 (HT1) is a rare genetic disease that results from mutations of the tyrosine catabolism enzyme fumarylacetoacetate hydrolase (FAH) for which there is currently no cure." (PMID 35668715, 2022). "HT-1 is a severe human genetic disease caused by a mutation in the gene encoding for the last enzyme of the tyrosine catabolism pathway, fumarylacetoacetase (FAH)." (PMID 33497373, 2021). "Hereditary tyrosinemia type I is a fatal genetic disease caused by loss-of-function of fumarylacetoacetate hydrolase (FAH) enzyme, a key protein in the tyrosine metabolic pathway." (PMID 31117296, 2019). "HTI is a fatal genetic disease caused by a mutation in the last enzyme of the catabolic pathway, fumarylacetoacetate hydrolase (FAH)." (PMID 30213032, 2018). "FAH−/− rabbits display liver and kidney manifestations of the human genetic disorder but also have frequent ocular alterations (mostly corneal keratitis)." (PMID 28053091, 2017). "Hereditary tyrosinemia type 1 (HT-1) is a rare genetic disorder with autosomal recessive inheritance resulting from the lack of the enzyme fumarylacetoacetate hydrolase (FAH)." (PMID 39050308, 2024).
tumor (6 papers, 2015 to 2023). "Moreover, tumours generated under particular conditions of induced liver injury in mice with an FAH‐deficient genetic background closely resemble human HCC under alcohol‐induced and c‐Myc‐altered conditions." (PMID 37997519, 2023). "The results showed slight upregulation of the FAH gene in tumor tissue when compared with normal tissues." (PMID 33218190, 2020). "To support our results, we analyzed the expression levels of FAH using The Cancer Genome Atlas (TCGA) data in liver hepatocellular carcinoma (LIHC), for which normal-tumor matched RNAseq expression data were available." (PMID 33218190, 2020).
infection (3 papers, 2016 to 2025). The state of being infected such as from the introduction of a foreign agent such as serum, vaccine, antigenic substance or organism. "FAH knockdown resulted in increased HBV replication in the primary human hepatocyte infection system and conventional HBV-transfected HepG2 clone." (PMID 40048440, 2025). "Huh7 cells were transduced with lentivirus expressing WT, the p.R142G variant of FAH, or a green fluorescent protein (GFP) control at the same calculated multiplicity of infection." (PMID 27397503, 2016).
kidney disease (1 paper, 2015). "A defect in FAH results in the accumulation of FAA that can lead to oxidative stress and severe liver and kidney disease." (PMID 26283601, 2015).
FAH also shares sentences with these, for which no sentence is quoted: hypermethioninemia (3 papers); Hypertyrosinemia (2); Hypoglycemia (2); liver cirrhosis (2); liver fibrosis (2); malaria (2); Ascites (1); bacterial infections (1); cardiomyopathy (1); cholestasis (1); chronic liver failure (1); coagulopathy (1); colorectal carcinoma (1); cystic fibrosis (1); diabetes (1); Duchenne muscular dystrophy (1); Fanconi syndrome (1); heart diseases (1); hemophilia B (1); Hepatosplenomegaly (1); hyperhomocysteinemia (1); hypophosphatemia (1); kidney inflammation (1); Leber congenital amaurosis (1); liver (1); Obesity (1); ovarian carcinoma (1); parasitemia (1); porphyria (1); prostate carcinoma (1).
A further 6 diseases each share a sentence with FAH in 1 paper.